SFTPB (surfactant protein B)
Diseases named in the same sentence as SFTPB in open-access papers (continued):
Sharing a sentence is not in itself a finding about the gene and the disease.
cancer (continued). "Further investigations of the remaining genes such as FN1, EEF1A1, COL1A1, SFTPB, SFTPC, and ATP1A1 will shed light on the identification of novel biomarker genes for a pan-cancer cohort." (PMID 31324856, 2019). "On the other hand, the expression patterns of genes like SFTPB, LAMC2, KRT7 and CLIC6 varied significantly among different cancer types, suggesting that these genes may play context‐dependent roles." (PMID 39828988, 2025). "The expression of TPX2, TOP2A and MYBL23 was significantly higher in cancer tissues than in paracancerous tissues, but SFTPB was lower in cancer tissues, and that TPX2, TOP2A and MYBL23 high expression groups had poorer OS prognosis, while SFTPB high expression group had better OS (p < 0.05)." (PMID 37407689, 2023). "AT2 markers SFTPB and ABCA3 were simultaneously expressed in a large proportion of cancer cells." (PMID 35874770, 2022). "Interestingly, the mouse SFTPB, which has the tail CFQTPHL, was also shown to be increased in plasma of a cancer model." (PMID 34268295, 2021). "Phenotype scanning revealed that seven out of the thirteen identified proteins (KDELC2, GSTP1, CTSS, CPNE1, ISLR2, SFTPB, and ICAM5) were associated with other traits, but none of these traits were likely to bias the associations between identified proteins and cancers." (PMID 37735436, 2023). "KRT19, CEACAM5, EPCAM, DSG3, SFTPA, SFTPC and SFTPB mRNA levels were initially validated by real-time reverse transcription PCR-based quantification in 16 NSCLC tumors and 22 LNs and 12 PB samples from individuals without known cancer." (PMID 23671585, 2013).
tumor (16 papers, 2012 to 2026). "Here, we found that 34%-43% of rNSCLC patients have lower surfactant protein B precursor (pro-SFTPB) expression in tumor compared to adjacent tissues, and this low expression of pro-SFTPB is associated with low major pathological response to neoadjuvant chemoimmunotherapy and recurrence in rNSCLC." (PMID 42157944, 2026). "Furthermore, an experiment in which a lung metastasis model was used showed that downregulation of pro-SFTPB significantly increased the number of tumor colonies in the lungs." (PMID 37946295, 2023). "Animal experiments showed that whereas subcutaneous injection of 1 × 106 H1299 cells resulted in tumor formation in 67% of mice within 3 weeks, injection of H1299 cells in which pro-SFTPB had been downregulated resulted in tumor formation in 100% of the animals." (PMID 37946295, 2023). "This stemness-associated signature integrates developmental drivers such as PTPRH, AHNAK2, PCDH7, metabolic regulators CPS1, SFTPB, and hypoxia-responsive factors such as TCN1, TMPRSS11E, reflecting the multifaceted nature of OSA-induced tumor evolution." (PMID 41584048, 2026). "In order to identify the key regulators in the ICD risk subgroups, first we verified the mRNA expression levels of these eight genes, and we found that only SFTPB and SERPIND1 were highly expressed in normal tissues, whereas FAM83A, FDCSP, KRT6A, RHOV and TPX2 were highly expressed in tumor tissues." (PMID 39247599, 2024). "Finally, we demonstrated that the reduction of SFTPB mRNA in NSCLC disrupts the negative regulation of pro-SFTPB on eIF4F complex formation, leading to activation of the eIF4F translation pathway and ultimately promoting tumor stemness and immune escape." (PMID 42157944, 2026). "The proportion of SFTPB+ DN T cells (C7) was higher in IA compared to MIA and N, whereas the proportion of ANKRD36C+ DN T cells (C4) in MIA was higher compared to IA but similar to N. Additionally, the proportion of Treg cells increased along with tumor progression." (PMID 37991139, 2023). "Of note, the only patient with a diagnosis of small‐cell lung cancer and RNA data (Patient 4) had RNA profiles from two tumor sites that were similar to each other and distinct from the other NSCLC tumors with higher levels of several mucins and surfactant proteins (MUC4, MUC5B, MUC6, SFTPB)." (PMID 31747139, 2020).
infection (12 papers, 2015 to 2025). The state of being infected such as from the introduction of a foreign agent such as serum, vaccine, antigenic substance or organism. "Such unexpected findings included broader viral tropism; an intrapulmonary innate immune system generated by bystander lung cells, and a protective function against inflammation and infection by surfactant protein B (SP-B), playing an important role in signal transduction." (PMID 39028694, 2024). "Because the SFTPB promoter is specifically expressed in type II pneumocytes, SARS-CoV-2 only infects the distal lung region of SFTPB-hACE2 mice, and thus the pathology score was based on only this focal infection." (PMID 36457995, 2022). "However, SFTPB-hACE2 and SCGB1A1-hACE2 mice showed minimal clinical signs after infection." (PMID 36457995, 2022).
adenocarcinoma (8 papers, 2002 to 2021). A common cancer characterized by the presence of malignant glandular cells. "Thyroid transcription factor-1 showed the same sensitivity (84.6%) as napsin for adenocarcinoma, whereas surfactant protein-A and surfactant protein-B showed lower sensitivities." (PMID 12698189, 2003).
respiratory diseases (4 papers, 2012 to 2024). "Initial testing for genetic causes of respiratory disease and PAH (including sequencing for FOXF1, SFTPB, SFTPC, ABCA3) was negative." (PMID 36878902, 2023).
SFTPB also shares sentences with these, for which no sentence is quoted: chronic obstructive pulmonary disease (9 papers); genetic disorders (4); inflammation (4); Respiratory distress (4); acute respiratory failure (3); bronchopulmonary dysplasia (3); Hydrocephalus (3); Interstitial pneumonitis (3); Sepsis (3); autoimmune PAP (2); chronic bronchitis (2); coronary heart disease (2); diabetes mellitus type 2 (2); emphysema (2); idiopathic intracranial hypertension (2); idiopathic pulmonary fibrosis (2); influenza (2); kidney disease (2); large cell carcinoma (2); protein deficiency (2); small cell carcinoma (2); viral infection (2); acute lung injury (1); Adult Respiratory Distress Syndrome (1); airway allergy (1); Allergy (1); aortic atherosclerosis (1); aortic stenosis (1); autoimmune disease (1); Autoimmunity (1).
A further 46 diseases each share a sentence with SFTPB in 1 paper.